RRM2 (ribonucleotide reductase regulatory subunit M2)
Diseases named in the same sentence as RRM2 in open-access papers (continued):
Sharing a sentence is not in itself a finding about the gene and the disease.
bladder cancer (19 papers, 2014 to 2025). "Our data suggested that RRM1 and RRM2 overexpression could be associated with the progression of bladder cancer." (PMID 26658059, 2015). "In particular, we confirmed RRM2 expression and function in bladder cancer in our clinical samples and cell lines." (PMID 35740608, 2022). "We used a panel of bladder cancer cell lines and primary tissues to confirm reports that RRM2 is elevated in bladder cancer." (PMID 28289079, 2017). "Our present study indicates that RRM1 and RRM2 are involved in gemcitabine resistance in human bladder cancer." (PMID 26658059, 2015). "Our study found that RRM1 and RRM2 were expressed in clinical bladder cancer tissues and bladder cancer cell lines." (PMID 26658059, 2015). "Immunohistochemical analysis was performed to assay RRM1 and RRM2 expression in surgically resected specimens of bladder cancer." (PMID 26658059, 2015). "RT112-Gr cells were left untreated or were treated with 45nM Gemcitabine (GEM), RNAi-mediated Knockdown of RRM1 and RRM2 in RT112-Gr bladder cancer cells were left untreated or were treated with 45nM Gemcitabine (GEM)." (PMID 26658059, 2015). "This is supported by the finding that knockdown of RRM2 protein markedly inhibited cell growth of UM-UC-3 bladder cancer cells." (PMID 24637958, 2014). "Finally, we clarified the protein expression of RRM2 in pan-cancer and researched the biological functions of RRM2 in bladder cancer (BLCA) in vitro." (PMID 35740608, 2022). "Additionally, multiple Cox regression analysis showed that RRM2 was an independent prognostic factor in bladder cancer (BLCA)." (PMID 35740608, 2022). "This complementation‐based strategy might be especially useful for treating more aggressive bladder cancers since increased levels of cellular RRM2 predict a poorer prognosis." (PMID 28289079, 2017). "RRM1 and RRM2 gene expression might be a predictive marker for the efficacy of gemcitabine therapy in bladder cancer patients." (PMID 26658059, 2015). "This is the first report of RRM1 and RRM2 protein overexpression in bladder cancer." (PMID 26658059, 2015). "In this study, a gemcitabine-resistant human bladder cancer cell line was established, and the role of RRM1 and RRM2 in the development of gemcitabine resistance was initially investigated." (PMID 26658059, 2015). "In bladder cancer cell lines, RT-PCR results demonstrated that RT112-Gr cells had significantly increased in the levels of RRM1 and RRM2 mRNA compared with the parental cells(p<0.001), respectively." (PMID 26658059, 2015). "However, there is limited information concerning RRM1 and RRM2 protein expression in bladder cancer, and to our knowledge no reports exist describing the role of RRM in the process of drug resistance in bladder cancer." (PMID 26658059, 2015).
gastric cancer (18 papers, 2010 to 2025). A primary or metastatic malignant neoplasm involving the stomach. "An example is SNHG4 miR-204-5p sponges; they increase the expression of RRM2 which causes the occurrence of gastric cancer." (PMID 36672893, 2023). "RRM2, an upstream regulator of the ovarian cancer cell cycle, has also been shown to promote gastric cancer cell invasiveness and migration." (PMID 40625451, 2024). "The reduced level of RRM2 after combination treatment was validated by Western blotting and immunofluorescence in gastric cancer cells." (PMID 37033615, 2023). "Mechanismly, the combination of HZ-A-018 and 5-FU remarkably reduced the expression of RRM2, which played an essential role in proliferation and drug sensitivity in gastric cancer cells." (PMID 37033615, 2023). "Herein, we found that overexpression of RRM2 not only accelerated cell growth, but also conferred gastric cancer cells with 5-FU resistance." (PMID 37033615, 2023). "The role of RRM2 in the proliferation and drug sensitivity of gastric cancer cells was determined by knocking down (KD) or overexpressing (OE) RRM2 before treatment with 5-FU, HZ-A-018 or the combination." (PMID 37033615, 2023). "For gastric cancer cell, overexpression of RRM2 promotes their invasiveness via AKT/NF-κB signaling pathway." (PMID 31139013, 2019). "Additionally, RRM2 regulated the invasiveness of gastric cancer cells through Akt/NF-kB signaling pathway." (PMID 38820515, 2024). "In gastric cancer, RRM2 overexpression has been found to enhance invasiveness." (PMID 40625451, 2024). "Knocking down of RRM2 significantly perturbed cell growth rate and meanwhile sensitized gastric cancer cells to chemotherapy, suggesting the possibility of insufficient suppression of RRM2 by using HZ-A-018 and the existence of alternative molecular targets of HZ-A-018 in gastric cancer cells." (PMID 37033615, 2023). "Herein, HZ-A-018 presented stronger anti-proliferation activity than ACP-196 in gastric cancer cells, and could sensitize 5-FU via the suppression of RRM2 both in vitro and in vivo." (PMID 37033615, 2023). "To conclude, our work demonstrated the anti-cancer activity of HZ-A-018 in gastric cancer, and demonstrated the synergistic effects of combination treatment with HZ-A-018 and 5-FU through the inhibition of RRM2 via AKT/S6 suppression, thereby providing a novel therapeutic strategy in gastric cancer." (PMID 37033615, 2023). "Although there was a study showed that RRM2 stimulation enhanced tumor invasiveness in gastric cancer cells, the correlation between RRM2 expression and 5-FU drug sensitivity remains largely unknown." (PMID 37033615, 2023). "Importantly, RRM2-KD significantly sensitized gastric cancer cells to the treatment of 5-FU, HZ-A-018 or the combination." (PMID 37033615, 2023). "More importantly, overexpression of RRM2 in gastric cancer cells promotes their invasiveness by regulating the AKT/NF-κB signaling pathway, and RRM2 increases tumor angiogenesis and growth by modulating the expression of thrombospondin-1 (TSP-1) and vascular endothelial growth factor (VEGF)." (PMID 31696057, 2019). "RRM2 subunit overexpression has also been observed in gastric cancer and bladder cancer tumors." (PMID 24637958, 2014). "However, a direct evidence that demonstrated the correlation between RRM2 expression and 5-FU sensitivity in gastric cancer is still lacking." (PMID 37033615, 2023).
ovarian carcinoma (15 papers, 2014 to 2025). A malignant neoplasm originating from the surface ovarian epithelium. "Of particular interest was ribonucleotide reductase regulatory subunit M2 (RRM2), the increase of which has been associated with all stages of ovarian cancer progression." (PMID 35008958, 2022). "The starBase database analysis showed a positive correlation between CDCA7 and RRM2 expression in ovarian cancer (p < 0.01)." (PMID 40630134, 2025). "The depletion of RRM2 has been reported to inhibit tumor growth in head and neck, lung, and ovarian cancers." (PMID 25648588, 2014). "Therefore, an anti-tumor strategy that interferes with the activity of RRM2 has the potential to inhibit the growth of ovarian cancer." (PMID 31673243, 2019). "Here, we used the human ovarian carcinoma SKOV3 cell line to construct a nude mouse subcutaneous transplantation model to investigate whether RRM2 gene therapy was a novel therapeutic option for the treatment of epithelial ovarian cancer." (PMID 31673243, 2019). "RRM2 gene silencing may be a potential treatment regimen for ovarian cancer in future." (PMID 31673243, 2019). "Also, a higher expression of RRM2 total protein was observed in the primary tissues of BRCA, ovarian cancer, colon cancer, clear cell RCC, and UCEC." (PMID 36202136, 2022). "Moreover, the GEPIA database analysis indicated that RRM2 expression was significantly higher in ovarian cancer tissues compared to adjacent non-cancerous tissues (p < 0.05)." (PMID 40630134, 2025). "Previously, we have demonstrated the synergistic inhibitory effect of RNA interference technology combined with gemcitabine and cisplatin in SKOV3/DDP cells; however, no study has explored whether RRM2 gene therapy can also reverse ovarian cancer resistance to cisplatin in vivo." (PMID 31673243, 2019).
neuroblastoma (13 papers, 2013 to 2026). Neuroblastoma (NB) is the most common solid, extracranial childhood tumor. "Previous studies indicated that in neuroblastoma, a highly malignant brain tumor, patients with high RRM2 expression are associated with a worse prognosis." (PMID 34895038, 2021). "Suppression of RRM2 inhibits cell proliferation, causes cell cycle arrest, and promotes the apoptosis of human neuroblastoma cells." (PMID 33123291, 2020). "pinpointed RRM2 as a potential dependency factor, a finding that was bolstered by the observed growth inhibition following in vitro knockdown and the hastened tumor development in a neuroblastoma zebra fish model that coexpressed human RRM2 with MYCN." (PMID 40625451, 2024). "With this approach we identified four genes that are highly over expressed in high-risk neuroblastoma (CHAF1A, RRM2, MCM3, and MCM6) whose expression strongly correlates with poor outcomes." (PMID 24348903, 2013). "RRM2 is also upregulated in neuroblastoma tissues and is closely related to its clinical stages." (PMID 35204799, 2022). "In addition, RRM2 could affect cell proliferation—specifically, inhibition of the cell cycle, which is manifested as the apoptosis of human neuroblastoma cells." (PMID 35204799, 2022). "We previously presented RRM2, the regulatory component of the ribonucleotide reductase (RNR) enzyme, as novel dependency in neuroblastoma (NB), in keeping with its role in RS resistance." (PMID 41741413, 2026). "Altogether, this study paves the way for further preclinical testing of second generation RRM2 and CHK1 inhibitors such as TAS1553 and SRA737 in neuroblastoma and sarcomas." (PMID 41741413, 2026). "A combination of RRM2 and CHK1 inhibitors has shown synergistic effects in neuroblastoma in vitro and in vivo." (PMID 38124207, 2023).
pancreatic adenocarcinoma (13 papers, 2007 to 2024). "Collectively, the present study is the first to investigate cyclin F and SPDL1 proteins in pancreatic adenocarcinoma, and one of the few that assessed RRM2 in this group of cancer patients." (PMID 33670609, 2021). "RRM2 enhances the invasive capacity of pancreatic adenocarcinoma cells in a NF-kappaB-dependent manner, and RRM2 overexpression can increase angiogenesis by down-regulating thrombspondin-1 and increasing production of VEGF." (PMID 25213022, 2014). "Likewise, RRM2 mRNA was significantly elevated in pancreatic adenocarcinoma cells comparatively to their normal counterparts (p < 0.0001)." (PMID 33670609, 2021). "It has been indicated that RRM2 is involved in the pathogenesis of pancreas adenocarcinoma." (PMID 32193399, 2020). "In addition, inhibition of RRM2 mRNA expression in vitro with the use of interference RNA enhanced chemosensitivity of pancreatic adenocarcinomas to gemcitabine." (PMID 18414411, 2008). "Duxbury & Whang found RRM2 induced NFκB activation of MMP9 and enhanced cellular invasiveness in pancreatic adenocarcinoma cells." (PMID 26001082, 2015). "Our IHC results are more consistent with the conclusions of the Xie study, who have shown no prognostic value of RRM2 immunoexpression in 117 patients with resectable pancreatic adenocarcinoma." (PMID 33670609, 2021). "The total protein expression of RRM2 was strongly elevated in BRCA, KIRC, COAD, HNSC, LIHC, LUAD, OV, pancreatic adenocarcinoma (PAAD), and UCEC patients (P < 0.05, P < 0.001)." (PMID 36518297, 2022). "Importantly, based on the analysis of the TCGA data, we identified RRM2 mRNA expression as an independent negative prognostic factor for OS in pancreatic adenocarcinoma patients." (PMID 33670609, 2021). "For pancreatic adenocarcinoma (PAAD), we analyzed the TCGA-PAAD dataset (n = 183) and failed to observe significant differential expression of RRM2 in PAAD tissues compared to levels in normal tissues." (PMID 38635758, 2024).
colon cancer (12 papers, 2009 to 2025). "Since no information about RRM2 expression of READ was available in HPA database, we instead discovered RRM2 expression in colon cancer." (PMID 40770782, 2025). "To data, there are only a few studies reported the function of non-histone protein crotonylation, our research finds a new crotonylated protein RRM2 and identify its pro-cancer role in colon cancer." (PMID 38894712, 2024). "Another cis-SAGe with different properties from its parental genes is RRM2-C2orf48, which promotes cellular proliferation in colon cancer cells." (PMID 36527429, 2023). "Cellular proliferation was significantly reduced when RRM2-C2orf48 was silenced, suggesting that RRM2-C2orf48 regulated colon cancer cellular proliferation." (PMID 35627126, 2022). "Our recent study had also shown that the RRM2 protein level in human colon cancer was positively correlated to the metastasis of colon cancer, and elevated RRM2 may serve as a potential biomarker for metastasis of colon cancer." (PMID 19250552, 2009). "However, whether RRM2 plays a role in cisplatin resistance in colon cancer and by what mechanism are still unknown." (PMID 38894712, 2024). "RRM2 expression levels in colon cancer patients’ tumor tissues ranged from moderate to low to no detectable protein expression." (PMID 40770782, 2025).
esophageal cancer (11 papers, 2018 to 2025). A primary or metastatic malignant neoplasm involving the esophagus. "RRM2 is an oncogene playing a key role in tumorigenesis and cancer progression, including colorectal and oesophageal cancers." (PMID 34202278, 2021). "Previous studies indicated that RRM2 inhibition enhanced radiosensitivity in esophageal cancer." (PMID 33858512, 2021). "RRM2 inhibitor Osalmid has been shown to enhance the radiosensitivity of esophageal cancer." (PMID 34895038, 2021).
renal cell carcinoma (11 papers, 2019 to 2025). "Recent studies have demonstrated that the dysregulation of RRM2 is associated with certain types of malignancy, including renal cell carcinoma, lung cancer, glioblastoma, and breast cancer." (PMID 39766842, 2024). "In renal cell carcinoma, RRM2 silencing enhances the antitumor activity of PD-L1 blockade and sunitinib, likely by modulating immune evasion pathways." (PMID 40493217, 2025). "In renal cell carcinoma, RRM2 silencing can increase renal cell carcinoma’s sensitivity to sunitinib, as well as improving the anti-tumor efficacy of PD-L1 blockade." (PMID 39766842, 2024). "RRM2 overexpression plays a key role in sunitinib resistance in patients with renal cell carcinoma and that RRM2 competes with UBE3A to prevent ANXA1 degradation." (PMID 34319001, 2021). "In renal cell carcinoma cells, miR-99a-3p significantly inhibits cell proliferation and colony formation through regulating ribonucleotide reductase regulatory subunit-M2." (PMID 31795200, 2019). "Inhibition of RRM2 can overcome sunitinib-resistance in renal cell carcinoma." (PMID 39884577, 2025).
retinoblastoma (10 papers, 2021 to 2024). A malignant tumor that originates in the nuclear layer of the retina. "This is strengthened by the observation that the mRNAs for E2F1 and E2F2, cyclins A1, A2 and cyclins E1 and E2 as well as the mRNAs for the ribonucleotide synthase subunits RRM1 and RRM2 are high in retinoblastoma primary tumors." (PMID 38332874, 2024). "LncRNA HOTAIR inhibits apoptosis of retinoblastoma cells by upregulating ribonucleotide reductase regulatory subunit M2 (RRM2) for phosphorylating AKT, reverted by HOTAIR knockdown." (PMID 36230902, 2022). "As shown in the protein network plot for retinoblastoma-related genes, SMC2, HMGB1, WEE1, RRM2, and POLA1 proteins showed an association with other proteins." (PMID 34646884, 2021). "The STRING database plotted their protein network, and the five proteins WEE1, SMC2, HMGB1, RRM2, and POLA1 that were most associated with the range of activity involved in tumorigenesis and retinoblastoma progression were selected from 366 genes." (PMID 34646884, 2021). "Two studies similarly examined retinoblastoma gene expression profiles in healthy individuals and finally showed that RRM2 can play an important role in cell division and its different phases." (PMID 34646884, 2021). "For instance, studies have shown that the constitutively active retinoblastoma tumor suppressor can attenuate the expression of specific dNTP synthetic cellular enzymes, including DHFR, RRM1, RRM2, and thymidylate synthase (TS)." (PMID 39339888, 2024). "Bioinformatics analysis of multi-omics data also identified TTK, RRM2, and CDK1 as potential retinoblastoma molecular biomarkers." (PMID 38012786, 2023). "WEE1, SMC2, HMGB1, RRM2, and POLA1 proteins were also observed to be involved in the progression and invasion of retinoblastoma; SLC24A2 and DTX4 in age-related macular degeneration; and EPHB6, EFNB3, and SHC1 in glaucoma." (PMID 34646884, 2021).